SOS2 (SOS Ras/Rho guanine nucleotide exchange factor 2)
Diseases named in the same sentence as SOS2 in open-access papers:
SOS2 is named in the same sentence as 48 diseases in open-access papers, as found by Europe PMC text mining. Sharing a sentence is not in itself a finding about the gene and the disease. The quoted sentences say what the papers report.
Noonan syndrome (14 papers, 2013 to 2025). "The patient was found to have a missense variant in SOS2, a gene known to be associated with Noonan syndrome." (PMID 38755526, 2024). "SOS2 gene (MIM: 601247) associated with Noonan syndrome 9 (MIM: 616559) was found in family GEL-S01 with one affected individual (GEL-S01-01) with a heterozygous missense variant (c.800T>A p.(Met267Lys))." (PMID 38755526, 2024). "The KRAS gene, along with LZTR1 and SOS2, is one of the three Noonan syndrome-causing genes in this group." (PMID 35813072, 2022). "Mutations in SOS2 have been reported in individuals with Noonan syndrome." (PMID 36914875, 2023). "A recent study demonstrated that SOS2 mutation causes Noonan syndrome." (PMID 35141295, 2021). "Mutations associated with Noonan syndrome alone include CBL, BRAF, KRAS, LZTR1, MAP2K1 (MEK1), NRAS, PTPN11, RAF1, RIT1, SOS1 and SOS2." (PMID 38550930, 2023). "These include genes related to Noonan syndrome (SOS2), sitting height (A2M), and skeletal disproportion (BCAS3), further emphasizing the need to closely evaluate skeletal phenotype when assessing a child with SS." (PMID 32939436, 2020). "A previous study found that SOS2 was homologous to SOS1, the second gene frequently related to Noonan syndrome." (PMID 35141295, 2021). "SOS1 and KRAS, but not SOS2, have been implicated in human rasopathies, including mutations in SOS1 and KRAS in Noonan syndrome and KRAS mutations in cardiofaciocutaneous syndrome." (PMID 23761422, 2013).
RASopathies (7 papers, 2013 to 2025). "While SOS2 variants are less common, emerging evidence suggests that they contribute to RASopathies through similar mechanisms, albeit with distinct tissue-specific effects due to differences in expression patterns and functional interactions." (PMID 40332000, 2025). "While SOS2 variants are rare, they have been identified in some patients with NS phenotypes, further expanding the genotype–phenotype spectrum of RASopathies." (PMID 40332000, 2025). "Specific SOS2 mutations were also identified in some RASopathies and cancer forms." (PMID 34205562, 2021). "The carrier of the SOS2 p.E9G (Case 6) presented typical facial features of RASopathies, gonadal dysgenesis (CR, low TTV, anejaculation, and hypogonadism), and impaired mobility and cognitive and intellectual performance." (PMID 38654924, 2024). "Similar to pathogenic and likely pathogenic variants, heterozygous VOUS were identified in RASopathy genes (SOS1, SOS2, and RAF1), inherited from unaffected parents." (PMID 36959127, 2023). "BRAF, CBL, NF1, PTPN11, RAF1, SOS1 and SOS2 contain at least 20 phosphosites each, and they account for 326 of the phosphosites identified in RASopathy proteins (61% of the total)." (PMID 34229750, 2021). "Many of the RASopathy-associated genes are in gene families: RAF (BRAF and RAF1), RAS (HRAS, KRAS, MRAS, NRAS, RIT1, and RRAS2), MAP2K (MAP2K1 and MAP2K2), and SOS (SOS1 and SOS2)." (PMID 40496714, 2025). "Pathologies linked to SOS2 alterations include different inherited proliferative/developmental disorders (RASopathies), as well as sporadic tumors and other nontumoral diseases." (PMID 34205562, 2021).
lung adenocarcinoma (5 papers, 2020 to 2024). A carcinoma that arises from the lung and is characterized by the presence of malignant glandular epithelial cells. "Here, we investigate SOS1 and SOS2 as potential therapeutic targets in EGFR-mutated lung adenocarcinoma cells." (PMID 32897190, 2020). "The impact of genetic ablation of SOS1 or SOS2 is evaluated in a murine model of KRASG12D-driven lung adenocarcinoma (LUAD)." (PMID 37730692, 2023). "Here, we show that SOS2 modulates the threshold of epidermal growth factor receptor (EGFR) signaling to regulate the efficacy of and resistance to the EGFR tyrosine kinase inhibitor (EGFR-TKI) osimertinib in lung adenocarcinoma (LUAD)." (PMID 38073064, 2024). "Here, we show that SOS2 modulates the threshold of epidermal growth factor receptor (EGFR) signaling to regulate the efficacy of and resistance to the EGFR-TKI osimertinib in lung adenocarcinoma (LUAD)." (PMID 37425733, 2023).
prostate carcinoma (2 papers, 2018). A carcinoma that arises from epithelial cells of the prostate gland. "The four genes CDH1, MYC, SOS2, and CDKN1A are obtained from the prostate cancer network." (PMID 29670664, 2018).
renal cell carcinoma (2 papers, 2017 to 2022). "Renal Cell Carcinoma Pathway assigned of 49/66 CNA genes RAF1 (16/26) and VHL (14/26) as G1 top-ranks with Fisher’s exact test p-values of 0.00228 and 0.0004437 (respectively) and SOS2 (7/20), HGF (4/20) and BRAF (3/20) as G3 top-ranks with p-values of 0.17, 0.51 and 0.075, respectively." (PMID 28486536, 2017).
type 2 diabetes (2 papers, 2017 to 2019). "Similarly, we observed that SOS2 was another seeder gene that was linked with SRC, INSRR, EGFR, FGFR1, PGFRA and PGFRB gene signatures that were significantly associated with insulin resistance and type 2 diabetes." (PMID 28179884, 2017).
alexithymia (1 paper, 2022). An agnosia that is a deficiency in understanding, processing, or describing emotions. "For PTPN11/NSML, SHOC2, CBL, and SOS2, alexithymia was more present than expected." (PMID 36012976, 2022). "Regarding psychopathology, the findings largely confirmed our hypotheses, insofar as alexithymia was significantly present in two groups, PTPN11 and SOS1, while it was credibly present in PTPN11/NSML, SHOC2, CBL, and SOS2 as well." (PMID 36012976, 2022).
Alzheimer disease (1 paper, 2021). A progressive, neurodegenerative disease characterized by loss of function and death of nerve cells in several areas of the brain leading to loss of cognitive function such as memory and language. "In particular, two single nucleotide polymorphisms (SNPs) were characterized in SOS2 that are significantly associated with late-onset Alzheimer’s disease, suggesting that SOS2 may be a male specific risk factor for Alzheimer’s disease." (PMID 34205562, 2021). "Thus, SOS2 has been proposed as a susceptibility locus for initiation of Alzheimer’s disease." (PMID 34205562, 2021).
attention deficit-hyperactivity disorder (1 paper, 2014). A disorder characterized by a marked pattern of inattention and/or hyperactivity-impulsivity that is inconsistent with developmental level and clearly interferes with functioning in at least two settings (e.g. at home and at school). "YWHAZ is cocited with FZD7 in a paper on attention-deficit/hyperactivity disorder, with ATXN1 in a paper on the interaction of Akt-Phosphorylated Ataxin-1 with 14-3-3, and with SOS2 in a paper on epidermal growth factor receptor phosphorylation sites." (PMID 25148247, 2014).
chronic hepatitis (1 paper, 2018). An active inflammatory process affecting the liver for more than six months. "MAP2K7 and MAPK14 were highly expressed in chronic hepatitis; LAT, SOS2, and BCL‐10 were highly expressed in normal tissues; PTPN6, LCK, and CTLA4 were highly expressed in CS." (PMID 30259695, 2018).
developmental delay (1 paper, 2024). "The patient carrying the SOS2 p.E9G variant presented severe developmental delay (DD) with impaired cognitive and intellectual performance (details below)." (PMID 38654924, 2024).
epilepsy (1 paper, 2024). A brain disorder characterized by episodes of abnormally increased neuronal discharge resulting in transient episodes of sensory or motor neurological dysfunction, or psychic dysfunction. "He had also been diagnosed with Lennox–Gastaut syndrome, characterized by early-onset epilepsy and pancreatic cancer that are not typically observed in SOS2-linked NS." (PMID 38654924, 2024).
glioblastoma (1 paper, 2021). The most malignant astrocytic tumor (WHO grade IV). "Recent analysis of gene expression profiles has also reported MuD-dependent upregulation of SOS2 expression in cohorts of TCGA glioblastomas (GBM), and a correlation between high expression of the two genes and longer survival of proneural GBM patients." (PMID 34205562, 2021).
glioma (1 paper, 2023). A benign or malignant brain and spinal cord tumor that arises from glial cells (astrocytes, oligodendrocytes, ependymal cells).
hypothyroidism (1 paper, 2020). Abnormally low levels of thyroid hormone. "At a gene level, PTPN11, NRAS, RASA2, SOS2, MAP2K1, and RAF1 were significantly associated with hypothyroidism, diastolic and systolic BP, birth weight, growth abnormality, subcutaneous adipose tissue, standing/sitting height ratio and body mass index." (PMID 33226994, 2020).
liver cancer (1 paper, 2021). An epithelial or non-epithelial malignant neoplasm that arises from the liver. "Our study identified sulfarotene as a selective inhibitor for the TRCs of HCC, which targets a novel RARα-SOS2-RAS signal nexus, shedding light on a new, promising strategy of target therapy for advanced liver cancer." (PMID 34479623, 2021).
lung carcinoma (1 paper, 2021). "Additionally, phosphoproteomic analysis of ALK-positive lung cancer cells with or without gilteritinib treatment revealed that gilteritinib significantly decreased phosphorylation of ALK and its adapter proteins such as IRS1/2, SOS2, or SH2B1." (PMID 33627640, 2021).
meningioma (1 paper, 2012). A generally slow growing tumor attached to the dura mater. "Considering inconsistent expression of SOS2/KRAS and JUN/FOS in fibroblastic meningioma, we speculated that activated Ras promoted tumor growth through the PI3K/Akt pathway, but not via ERK-c-Jun/c-Fos pathway." (PMID 23285163, 2012).
papilloma (1 paper, 2021). A benign epithelial neoplasm that projects above the surrounding epithelial surface and consists of villous or arborescent outgrowths of fibrovascular stroma. "In addition, SOS1 disruption (but not SOS2 ablation) delayed the onset of tumor initiation, decreased tumor growth, and prevented malignant progression of papillomas when using the known DMBA/TPA model of chemically induced skin carcinogenesis in mice." (PMID 34205562, 2021).
periodontitis (1 paper, 2014). An acute or chronic inflammatory process that affects the tissues that surround and support the teeth. "Aside from the SOS2 to NIN region on chromosome 14, none of the other nine implicated loci overlapped with results from published GWAS of periodontitis." (PMID 24347629, 2014).
pulmonary valve stenosis (1 paper, 2022). The pathologic narrowing of the orifice of the pulmonary valve. "Among all the pathogenic variants, we found that patients with mutations in RIT1, SOS1, PTPN11, and SOS2 had common echocardiography figures characterized by pulmonary valve stenosis, while RAF1 patients had HCM." (PMID 35770001, 2022). "SOS1, RIT1, PTPN11, and SOS2 mutations showed common cardiac abnormalities such as pulmonary valve stenosis." (PMID 35770001, 2022). "SOS2-mutation carriers had pulmonary valve stenosis with regurgitation." (PMID 35770001, 2022). "RIT1, SOS1, PTPN11, and SOS2 had common echocardiography features characterized by pulmonary valve stenosis, while RAF1 was characterized by HCM." (PMID 35770001, 2022).
cancer (17 papers, 2019 to 2025). A tumor composed of atypical neoplastic, often pleomorphic cells that invade other tissues. "In contrast, transcriptional changes associated with both E2F targets and the G2M checkpoint were regulated by SOS2KO but not acute SOS1i treatment, consistent with previous studies showing a role for SOS2 in 3D spheroid growth of KRAS-mutated cancer cells." (PMID 38106234, 2023). "Since bypass RTK reactivation and/or tertiary EGFR mutations represent the majority of osimertinib-resistant cancers, these data suggest that targeting SOS2 has the potential to eliminate the majority of osimertinib resistance." (PMID 37425733, 2023). "The contributions of WT RAS to proliferation and transformation in RAS-mutated cancer cells places renewed interest in upstream signaling molecules, including the phosphatase/adaptor SHP2 and the RasGEFs SOS1 and SOS2, as potential therapeutic targets in RAS-mutated cancers." (PMID 33924994, 2021). "T2 specific variants were enriched in the cancer metastasis signaling (P = 4.33E‐03) including the matrix metalloproteases 11 (MMP11), low density lipoprotein receptor‐related protein 1(LRP1), mutS homolog 3 (MSH3), and son of sevenless homolog 2 (SOS2)." (PMID 30941903, 2019). "Results of cell culture models assessing the transformation capacity of different RAS-mutant tumor cells indicated that SOS2 inhibition may emerge as a therapeutic option in KRAS-mutant cancers." (PMID 31261735, 2019). "Among these, PLXNA3, HLA-E, DDX58, IKBKE, HSPA6, SOS2, and HSPA1A stood out, with significantly elevated expression levels in LIHC compared to other cancer types." (PMID 39000042, 2024). "Seven target genes, namely DDX5, SOS2, ACTG1, EZR, FN1, HCLS1 and PIK3R5, were involved in proteoglycans in cancer signaling pathway." (PMID 32293320, 2020). "In particular, diet-modulated miRNAs were able to target and interfere with several genes mainly involved in cancer signal transduction pathways (e.g., EGFR, RAC1, PLCG1, FOS, NRAS, SOS2, etc.)." (PMID 32911851, 2020). "This pattern of heterogeneity was similar when considering a broader list of pan-cancer driver genes, with private amplification events seen in ERBB3, RHEB, SOS1, SOS2, and EZH2." (PMID 30348992, 2019). "In particular, it has been reported that RTK–SOS2–WT RAS signaling, but not allosteric SOS2 activation, is a critical mediator of mutant KRAS-driven transformation by protecting KRAS-mutated cancer cells from anoikis." (PMID 34205562, 2021). "In contrast, we found that RTK-SOS2-WT RAS signaling, but not allosteric SOS2 activation, is a critical mediator of mutant KRAS-driven transformation by protecting KRAS-mutated cancer cells from anoikis." (PMID 33924994, 2021). "Indeed, multiple upstream regulators of Ras activation such as SOS1, SOS2, PTPN11, and GAB1 exhibit significant negative correlations with NF1 in the Cancer Dependency Map, supporting the importance of these genes as functionally opposing NF1 function." (PMID 40587782, 2025). "For example, the following top 100 MDS genes can be mentioned that are not yet covered by approved or experimental cancer or antineoplastic drugs [according to DrugBank, DGIdb, FDA6, HMDB, Tocris7, GeneCards databases]: GRB2, SOS1,SOS2, SHC1, GNB1, CREB1, GNG2, GNAQ, GNB5, GNAI2." (PMID 30728774, 2019).
tumor (14 papers, 2007 to 2025). "Somewhat surprisingly, these studies showed that CRISPR/Cas9-mediated removal of SOS2 also caused some reduction of tumor burden and percentage of Ki67-positive and pERK-positive cells in the tumoral masses." (PMID 37730692, 2023). "Stable overexpression of SOS2 significantly enhanced colony spheroid formation and subsequent formation of subcutaneous xenograft tumor nodes of these TRCs." (PMID 34479623, 2021). "We found that the volume and weight of tumor nodes derived from PDXs of high SOS2 expressors were larger than that of the low SOS2 expressors, suggesting that the tumor nodes of high SOS2 expressors retained the characteristics of the HCC TRCs." (PMID 34479623, 2021). "In the ERBB2 pathway, the ERBB2 gene is consistently the highest expressing linear gene among all the three tumor grades but, for circRNA, SOS2 has the highest expression across the grades." (PMID 32670866, 2020). "Our analysis identified several candidate genes, including EXOC5, PPP2R5E, and SOS2, and showed that PPP2R5E and SOS2 expression levels correlated with MuD level in tumor cells to some extent." (PMID 31616474, 2019). "TGFBR2, SMAD3, SMAD5, SOS1 and SOS2 were found to be lower expressed in VEGFA165 tumours compared with control tumours." (PMID 22045186, 2011). "List of genetically-based strategies to downregulate SOS2 gene in the indicated tumor cell lines." (PMID 34205562, 2021). "SOS2 gene silencing strategies in different tumor cell types." (PMID 34205562, 2021). "Analyses of SOS2 expression by qPCR from a cohort of 45 patients, as well as by IHC from a cohort of 237 HCC patients in which 127 had metastasis, revealed that the levels of SOS2 in both the primary and the metastatic tumor foci were higher than in the paired peritumor tissues." (PMID 34479623, 2021). "Interestingly, silencing of SOS2 in the same experimental setting also led to reduce lung tumor burden, suggesting that SOS2 may also be able to contribute to intrinsic tumor growth initiation under these experimental conditions." (PMID 37730692, 2023). "Consistent with this notion, genetically-mediated silencing of the human SOS2 gene by means of miRNAs or CRISPR/Cas9 also produces significant therapeutic benefits in different in vitro models, including human tumor cell lines." (PMID 34205562, 2021). "Functionally, reduction of SOS2 expression by shRNAs significantly impaired the abilities of HCC TRCs to form colony spheroids and of PLC/PRF/5-TRCs to grow subcutaneous xenograft tumor nodes in nude mice." (PMID 34479623, 2021). "Conversely, specific SOS2 functions, including a critical role in regulation of the RAS–PI3K/AKT signaling axis in keratinocytes and KRAS-driven tumor lines or in control of epidermal stem cell homeostasis, were also reported." (PMID 34205562, 2021). "In our study, qRT-PCR analysis showed SHC4 (15.85-fold), SOS2 (2.78-fold), CCDC6 (6.18-fold), and KRAS (5.92-fold) were up-regulated significantly in tumor tissues." (PMID 23285163, 2012). "Notable, genes involved in TGF-β signalling (SOS1, SOS2, SMAD5, LTBP3, TGFBR2, IRF7 and CREBZF) were found to be significantly (P<0.01) downregulated in the VEGFA165 tumours." (PMID 22045186, 2011). "Strikingly, our results showed that the absence of SOS1, but not SOS2, in the lungs of the recipient, injected mice dramatically reduced the tumor burden of KPB6-dependent lung tumors as compared to their SOS1/2WT/KRASWT WT counterparts." (PMID 37730692, 2023). "In the present study, we found that both human HCC tumor foci and the selected TRCs were among the high expressors for SOS2, but not for SOS1, which remained low and unchanged." (PMID 34479623, 2021). "Furthermore, analyses of the data gathered from human HCC patients by the Cancer Genome Atlas (TCGA) showed that the expression of SOS2 in tumor foci was higher than in the paired adjacent non-tumor tissues." (PMID 34479623, 2021).
SOS2 also shares sentences with these, for which no sentence is quoted: hepatocellular carcinoma (3 papers); breast carcinoma (2); gingival fibromatosis (2); infection (2); cardiac hypertrophy (1); cardiofaciocutaneous syndrome (1); coronary atherosclerosis (1); Dubin-Johnson syndrome (1); endometrial tumors (1); essential hypertension (1); gastroesophageal reflux disease (1); gonadal dysgenesis (1); hematologic malignancies (1); Hepatomegaly (1); Hypertension (1); hypogonadism (1); Inguinal hernia (1); Insulin resistance (1); LEOPARD syndrome (1); myeloid leukemia (1); Noonan syndrome 9 (1); ovarian carcinoma (1); pancreatic cancer (1); SARS-CoV infection (1); Splenomegaly (1).